TBATA (thymus, brain and testes associated)
Description:
May play a role in spermatid differentiation. Modulates thymic stromal cell proliferation and thymus function.
Synonyms: C10orf27; SPATIAL; FLJ32820
Tractability: No criterion of Open Targets' tractability assessment is met for any kind of drug.
Gene: Protein-coding gene on chromosome 10 (70,771,238 to 70,785,401, reverse strand). Ensembl gene ENSG00000166220.
Subcellular location: Cytoplasm, cytosol
Gene Ontology:
Molecular function: protein binding
Cellular component: ciliary basal body; cytosol
Genetic constraint (gnomAD): Loss-of-function variants: 41 observed, 36.51 expected, observed/expected ratio (o/e) 1.12, 90% interval 0.87 to 1.46. The upper end of that interval is the gene's LOEUF score, 1.46, which puts it in group 6 of 6, group 1 being the genes least tolerant of losing a copy. Missense variants: 408 observed, 418.33 expected, observed/expected ratio (o/e) 0.98, 90% interval 0.9 to 1.06. Synonymous variants: 170 observed, 161.28 expected, observed/expected ratio (o/e) 1.05, 90% interval 0.93 to 1.2.
Homologues: Orthologues: chimpanzee TBATA (97% identical), macaque TBATA (82% identical), pig TBATA (73% identical), rabbit TBATA (70% identical), mouse Tbata (66% identical), guinea pig TBATA (57% identical), rat Tbata (45% identical), tropical clawed frog tbata (34% identical), zebrafish tbata (28% identical).
Diseases named in the same sentence as TBATA in open-access papers:
TBATA is named in the same sentence as 1 disease in open-access papers, as found by Europe PMC text mining. Sharing a sentence is not in itself a finding about the gene and the disease. The quoted sentences say what the papers report.
multiple sclerosis (1 paper, 2024). A progressive autoimmune disorder affecting the central nervous system resulting in demyelination. "The TBATA protein regulates thymus function and has several common variants associated with multiple sclerosis susceptibility." (PMID 39112476, 2024).